SLC10A6 (solute carrier family 10 member 6)
Description:
Transports sulfoconjugated steroid hormones from the extracellular compartment into the cytosol in a sodium-dependent manner without hydrolysis. Steroid sulfate hormones are commonly considered to be biologically inactive metabolites, that may be activated by steroid sulfatases into free steroids. May play an important role by delivering sulfoconjugated steroids to specific target cells in reproductive organs (By similarity). May play a role transporting the estriol precursor 16alpha-hydroxydehydroepiandrosterone 3-sulfate (16a-OH-DHEAS) at the fetal blood vessel endothelium. Can also transport other sulfoconjugated molecules such as taurolithocholic acid-3-sulfate and sulfoconjugated pyrenes.
Synonyms: SOAT
Tractability: Antibody: its Gene Ontology location is reachable by antibodies, with high confidence; UniProt predicts a signal peptide or a membrane-spanning region.
Gene: Protein-coding gene on chromosome 4 (86,823,468 to 86,849,384, reverse strand). Ensembl gene ENSG00000145283.
Subcellular location: Membrane
Pathways (Reactome):
Transport of small molecules: SLC-mediated bile acid transport
Gene Ontology:
Molecular function: protein binding; bile acid:sodium symporter activity
Biological process: bile acid and bile salt transport; sodium-dependent organic anion transport
Cellular component: plasma membrane; membrane
Genetic constraint (gnomAD): Loss-of-function variants: 24 observed, 28.1 expected, observed/expected ratio (o/e) 0.85, 90% interval 0.62 to 1.2. The upper end of that interval is the gene's LOEUF score, 1.2, which puts it in group 5 of 6, group 1 being the genes least tolerant of losing a copy. Missense variants: 431 observed, 465.58 expected, observed/expected ratio (o/e) 0.93, 90% interval 0.86 to 1. Synonymous variants: 165 observed, 180.59 expected, observed/expected ratio (o/e) 0.91, 90% interval 0.8 to 1.04.
Homologues: Orthologues: chimpanzee SLC10A6 (99% identical), macaque SLC10A6 (98% identical), dog SLC10A6 (86% identical), pig SLC10A6 (82% identical), rabbit SLC10A6 (80% identical), guinea pig SLC10A6 (73% identical), mouse Slc10a6 (70% identical), rat Slc10a6 (69% identical), tropical clawed frog slc10a6 (48% identical). Paralogues in human: SLC10A2 (41% identical), SLC10A1 (32% identical), SLC10A4 (31% identical), SLC10A3 (24% identical), SLC10A5 (20% identical).
Diseases named in the same sentence as SLC10A6 in open-access papers:
SLC10A6 is named in the same sentence as 10 diseases in open-access papers, as found by Europe PMC text mining. Sharing a sentence is not in itself a finding about the gene and the disease. The quoted sentences say what the papers report.
breast carcinoma (1 paper, 2018). "SOAT expression was also analyzed in individual breast cancer samples at the protein level with the SLC10A6 (SOAT) C-13 antibody by IHC." (PMID 30186172, 2018). "In the present study, we analyzed expression of the SOAT (gene name SLC10A6) in breast cancer." (PMID 30186172, 2018).
Hypertension (1 paper, 2014). The presence of chronic increased pressure in the systemic arterial system. "‘Unknown I’ contained a diverse set of key driver genes such as SGK1, SIK1 and SLC10A6 (sodium metabolism and hypertension), MT2A and TSC22D3 (glucocorticoid signaling), GADD45G, ERRFI1, GPRC5A, and EGFR (cell growth and apoptosis), and CEBPB, CEBPD, and KCNA5 (heart development and function)." (PMID 25033284, 2014).
kidney cancer (1 paper, 2022). Primary or metastatic malignant neoplasm involving the kidney. "We observed that the mRNA expression level of ETV4 was significantly increased and the expression levels of SH2B3, FATE1, GRK5, MALL, HRH2, SEMA3G and SLC10A6 were decreased prominently in kidney cancer cells when compared with HK2 cell line." (PMID 36059531, 2022). "Furthermore, we detected the mRNA and protein expression levels of 8 epi-PCGs (ETV4, SH2B3, FATE1, GRK5, MALL, HRH2, SEMA3G and SLC10A6) in 4 human kidney cancer cell lines (786-O, A498, Caki-1 and ACHN) and the normal human renal tubular epithelial cell line HK2." (PMID 36059531, 2022).
cancer (1 paper, 2021). A tumor composed of atypical neoplastic, often pleomorphic cells that invade other tissues. "Six additional genes (SLC10A6, SLC22A1, SLC51A, SLC51B, SLCO1C1, SLCO4C1) were included to finally examine the expression of 15 genes encoding E1-S transporters in the total of 36 pairs of cancer and adjacent control tissue." (PMID 33917029, 2021).
infection (1 paper, 2022). The state of being infected such as from the introduction of a foreign agent such as serum, vaccine, antigenic substance or organism. "We used adenovirus (Ad)-SLC10A6 infection to overexpress SLC10A6 in SULT2B1-KO HT-29 cells, which was confirmed using immunofluorescent staining and western blotting." (PMID 35908039, 2022).
SLC10A6 also shares sentences with these, for which no sentence is quoted: atherosclerosis (1 paper); glaucoma (1); intrahepatic cholestasis (1); ischemic stroke (1); tumours (1).